ENSG00000256566 (novel protein)
Gene: Protein-coding gene on chromosome 20 (2,467,212 to 2,508,907, reverse strand). Ensembl gene ENSG00000256566.
Genetic constraint (gnomAD): Missense variants: 104 observed, 135.95 expected, observed/expected ratio (o/e) 0.76, 90% interval 0.65 to 0.9. Synonymous variants: 42 observed, 47.07 expected, observed/expected ratio (o/e) 0.89, 90% interval 0.7 to 1.15.